PATJ (PATJ crumbs cell polarity complex component)
Description:
Scaffolding protein that facilitates the localization of proteins to the cell membrane. Required for the correct formation of tight junctions and epithelial apico-basal polarity. Acts (via its L27 domain) as an apical connector and elongation factor for multistranded TJP1/ZO1 condensates that form a tight junction belt, thereby required for the formation of the tight junction-mediated cell barrier (By similarity). Positively regulates epithelial cell microtubule elongation and cell migration, possibly via facilitating localization of PRKCI/aPKC and PAR3D/PAR3 at the leading edge of migrating cells (By similarity). Plays a role in the correct reorientation of the microtubule-organizing center during epithelial migration (By similarity). May regulate the surface expression and/or function of ASIC3 in sensory neurons (By similarity). May recruit ARHGEF18 to apical cell-cell boundaries.
Synonyms: hINADL; CIPP; INADL; InaD-like
Tractability: Antibody: UniProt places it where antibodies can reach, with high confidence; its Gene Ontology location is reachable by antibodies, with high confidence. PROTAC: ubiquitination databases record sites on it.
Gene: Protein-coding gene on chromosome 1 (61,742,477 to 62,178,675, forward strand). Ensembl gene ENSG00000132849.
Subcellular location: Cell junction, tight junction; Apical cell membrane; Cytoplasm, perinuclear region
Subcellular location (Human Protein Atlas): Cell Junctions; Centriolar satellite; Cytosol
Pathways (Reactome):
Cell-Cell communication: Tight junction interactions
Disease: SARS-CoV-2 targets PDZ proteins in cell-cell junction
Gene Ontology:
Molecular function: protein binding
Biological process: establishment of apical/basal cell polarity; establishment or maintenance of epithelial cell apical/basal polarity; intracellular signal transduction; tight junction assembly
Cellular component: apical plasma membrane; bicellular tight junction; cell junction; centriolar satellite; extracellular exosome; perinuclear region of cytoplasm; apical junction complex; apical part of cell; cytoplasm; plasma membrane; tight junction
Genetic constraint (gnomAD): Loss-of-function variants: 86 observed, 122.36 expected, observed/expected ratio (o/e) 0.7, 90% interval 0.59 to 0.84. The upper end of that interval is the gene's LOEUF score, 0.84, which puts it in group 3 of 6, group 1 being the genes least tolerant of losing a copy. Missense variants: 1,375 observed, 1,557.1 expected, observed/expected ratio (o/e) 0.88, 90% interval 0.84 to 0.92. Synonymous variants: 511 observed, 584.41 expected, observed/expected ratio (o/e) 0.87, 90% interval 0.81 to 0.94.
Homologues: Orthologues: macaque PATJ (96% identical), chimpanzee PATJ (94% identical), dog PATJ (89% identical), pig PATJ (89% identical), rabbit PATJ (83% identical), mouse Patj (78% identical), rat Patj (77% identical), guinea pig PATJ (73% identical), tropical clawed frog patj (60% identical), zebrafish patj (53% identical), Caenorhabditis elegans mpz-1 (29% identical), Drosophila melanogaster Patj (13% identical), and 2 more. Paralogues in human: MPDZ (45% identical), FRMPD2 (11% identical), LNX2 (11% identical), LNX1 (10% identical), STXBP4 (4% identical).
Diseases named in the same sentence as PATJ in open-access papers:
PATJ is named in the same sentence as 31 diseases in open-access papers, as found by Europe PMC text mining. Sharing a sentence is not in itself a finding about the gene and the disease. The quoted sentences say what the papers report.
ischemic stroke (3 papers, 2020 to 2025). A stroke disorder caused by obstruction of blood flow to the brain, due to thrombotic (local blood clot formation) or embolic (due to a blood clot or other material traveling from another site) event. "Through GWAS studies we identified PATJ associated with functional outcome after ischemic stroke (IS)." (PMID 38368420, 2024). "PATJ SNP variants were associated with worse outcomes in ischemic stroke patients." (PMID 33005169, 2020). "A recent study reported that PATJ was downregulated after ischemic stroke, and the depletion of PATJ exhibited hallmarks of EndMT, which is beneficial for stroke recovery." (PMID 40253404, 2025).
Stroke (3 papers, 2022 to 2025). Sudden impairment of blood flow to a part of the brain due to occlusion or rupture of an artery to the brain. "Here we explored the relationship between PATJ expression, stroke functional outcome and the underlying molecular mechanisms." (PMID 38368420, 2024). "rs76221407 was the major SNP variant of the PATJ gene, which was associated with poor outcomes in stroke subjects after 3 months." (PMID 35326259, 2022). "The aims of this study were to disentangle the role of PATJ gene in stroke recovery, understanding how stroke affects PATJ expression depending on genetic variants, how this expression is related to stroke prognosis and which molecular mechanisms are involved in this process." (PMID 38368420, 2024). "After stroke, PATJ depletion triggers the loss of cell polarity that may explain YAP/TAZ translocation to the nucleus, which we observed it was accompanied by MUC1-C together with β-catenin and ZEB1." (PMID 38368420, 2024). "The aim of this study was to determine PATJ role in brain endothelial cells (ECs) in the context of stroke outcome." (PMID 38368420, 2024).
sleep disorder (2 papers, 2018 to 2021). A change from the patient's baseline sleeping pattern, in the hours slept and/or an alteration/dysfunction in the stages of sleep. "Findings include missense variants in established drug targets for sleep disorders (HCRTR1, HCRTR2), genes with roles in arousal (TRPC6, PNOC), and genes suggesting an obesity-hypersomnolence pathway (PNOC, PATJ)." (PMID 33568662, 2021). "We identify 123 loci of which 61 replicate in the 23andMe research cohort, including variants in established drug targets for sleep disorders (HCRTR1, HCRTR2), genes with roles in arousal (TRPC6, PNOC), and genes suggesting an obesity-hypersomnolence pathway (PNOC, PATJ)." (PMID 33568662, 2021).
brain tumor (1 paper, 2014). "In addition, Gαi and patJ were undetectable in both FSCs and prefollicle cells, but became detectable in more mature follicle cells, whereas partner of numb, brain tumor, and prospero appeared to be diffuse in or completely absent from FSCs and all follicle cells in the germarium." (PMID 24991805, 2014).
ciliopathy (1 paper, 2025). A genetic disorder of the cellular cilia or the cilia anchoring structures, the basal bodies, or of ciliary function. "Taken together, with the Crumbs cell polarity complex member PATJ, we add a new member to the large family of ciliopathy-related human disease proteins that is different from the classical ciliopathy protein classes, and may offer new perspectives for drug development." (PMID 40931526, 2025). "Using massively parallel sequencing, we here identified a pathogenic bi-allelic variant in the gene encoding PALS1-associated tight junction protein ([PATJ] also known as inactivation-no-afterpotential D-like, INADL) in an individual with ciliopathy." (PMID 40931526, 2025).
clear cell renal cell carcinoma (1 paper, 2020). "This study assessed PATJ expression in clear cell renal cell carcinoma (ccRCC) vs. normal tissues and associated with ccRCC progression and prognosis." (PMID 33005169, 2020).
colorectal cancer (1 paper, 2023). A primary or metastatic malignant neoplasm that affects the colon or rectum. "In a parallel approach, we tested another SMAP1-deficient colorectal cancer cell line, SW48 and observed indeed a similar behavior as with HCT116 cells: Deletion of Pals1 further reduced the cortical TJ marker ZO1 and displaced PATJ and Crb3a from the junctions." (PMID 36494580, 2023).
cyst (1 paper, 2023). A sac-like closed membranous structure that may be empty or contain fluid or amorphous material. "In this study, we demonstrate that knockout of PATJ in epithelial cells results in tight junction defects as well as in a disturbed apical-basal polarity and impaired lumen formation in three-dimensional cyst assays." (PMID 37878054, 2023). "In three-dimensional cyst assays, Pals1-binding deficient PATJ was not able to fully restore single-lumen formation but exhibited a phenotype similar to the knockout of Pals1." (PMID 37878054, 2023). "Of note, in contrast to other regulators of apical-basal polarity and TJ, such as Cingulin, PATJ-deficient cells establish the AMIS and a single lumen between two and four dividing cells correctly at first but fail to maintain this single lumen later on during cyst development." (PMID 37878054, 2023).
Hydrocephalus (1 paper, 2025). Hydrocephalus is an active distension of the ventricular system of the brain resulting from inadequate passage of CSF from its point of production within the cerebral ventricles to its point of absorption into the systemic circulation.
osteogenesis imperfecta (1 paper, 2016). Osteogenesis imperfecta (OI) comprises a heterogeneous group of genetic disorders characterized by increased bone fragility, low bone mass, and susceptibility to bone fractures with variable severity. "Apart from PATJ, the other gene that popped-up during meta-analysis was CRTAP gene which has been previously stated to play an important role in type II and type VII forms of recessive Osteogenesis Imperfecta, a rare form of the disease." (PMID 27651116, 2016).
tumor (13 papers, 2017 to 2026). "Reduced PATJ mRNA was associated with male patients, advanced tumor stages, grades, and ccB subtypes as well as poorer overall and DFS of patients." (PMID 33005169, 2020). "In conclusion, this study demonstrated that PATJ expression was downregulated in ccRCC and reduced PATJ level was associated with male patients and advanced tumor and poorer survival." (PMID 33005169, 2020). "Downregulation of PATJ mRNA was associated with male patients, advanced tumor stages, grades, and ccB subtypes as well as poorer overall and disease-free survival of patients." (PMID 33005169, 2020). "A decrease of PATJ in ccRCC was associated with the male advanced tumor, and poorer survival, suggesting that PATJ may be a useful prognostic biomarker and therapeutic target for ccRCC." (PMID 34996478, 2022). "Furthermore, PATJ protein was also significantly downregulated in ccRCC tissues and associated with advanced tumor pathologic, TNM stages and poorer overall." (PMID 33005169, 2020). "To validate expression and association of PATJ protein in ccRCC with patients’ pathological data, we utilized the UALCAN web tool and found that PATJ protein was reduced in ccRCC tissues vs. normal renal tissues and decrease in PATJ protein was associated with advanced tumor stages." (PMID 33005169, 2020). "Tumor transcriptome deconvolution identifies significant down-regulation of epithelial cell polarity, including PATJ (1p31), and fatty acid metabolism, including CYP4A11 (1p33), in cancer cells of tumors that develop metastatic progression." (PMID 41741714, 2026). "ZEB1 owes its pivotal role to the downregulation of E-cadherin and the regulation of further proteins involved in tumor progression, such as Crumbs3, HUGL2, and PATJ (Pals1-associated tight junction)." (PMID 34884646, 2021). "However, to date, it is still unknown how PATJ expression is dysregulated in human cancers, including ccRCC and whether restoration of PATJ expression could suppress tumor progression as a novel therapeutic target." (PMID 33005169, 2020). "Cluster 1 was characterized by upregulation of tumor-suppressing genes: HNF1B, CCNDBP1, PATJ, EPB41L3, MARVELD2, PTEN in conjunction with cell-cycle genes – GSPT1, GPR19, EAPP, KIT, CDKL1, and stem cell markers – RBBP5, NANOG, NCSTN, ERG, including quiescent stem cell markers—FOXP1, SMARCA2." (PMID 36348001, 2022). "Our own experimental data showed that PATJ protein was also significantly downregulated in ccRCC vs. normal tissues, which was associated with advanced tumor pathologic stage and TNM stage, and patients with a negative PATJ expressed tumor had a significantly shorter OS." (PMID 33005169, 2020).
cancer (11 papers, 2015 to 2026). A tumor composed of atypical neoplastic, often pleomorphic cells that invade other tissues. "Our study found that gene PATJ may play an important role in shaping the occurrence and progression of cancer and that its regulator TEAD1 could serve as a specific marker for LUAD diagnosis." (PMID 41415280, 2025). "Such an example may be illustrated by the recent discovery of LKB1, inactivated in a variety of cancers, as an activator of p114RhoGEF-driven junction assembly, which occurs via recruitment by cingulin and PATJ junctional adaptors." (PMID 25757376, 2015). "INADL, also known as PATJ, is a member of the cell polarity genes which have been recognized as critical factors in cancer progression." (PMID 27096627, 2016).
infection (2 papers, 2016 to 2024). The state of being infected such as from the introduction of a foreign agent such as serum, vaccine, antigenic substance or organism. "During infection, the expression pattern of PaTJ phage-encoding genes undergoes dynamic changes." (PMID 39772127, 2024). "We observed involvement of PATJ in restricting DENV infection, as our results revealed a significant inhibition in DENV-1 or DENV-2 infection in cells overexpressing PATJ protein as compared to vector controls." (PMID 27651116, 2016). "Akin to PATJ, CRTAP overexpression was also found to inhibit DENV-1 or DENV-2 infection compared to vector transfected controls as indicated by the percentage of total infected cells." (PMID 27651116, 2016).
PATJ also shares sentences with these, for which no sentence is quoted: breast cancer (6 papers); Pancreatic Cancer (2); asthma (1); autism (1); autosomal dominant polycystic kidney disease (1); breast tumor (1); cervical tumour (1); colon cancer (1); cystic kidney disease (1); Dengue Haemorrhagic fever (1); hepatocellular carcinoma (1); insomnia (1); lung carcinoma (1); meningioma (1); mesothelioma (1); Obesity (1); polycystic kidney disease (1); schizophrenia (1).